TLR7 (toll like receptor 7)
Diseases named in the same sentence as TLR7 in open-access papers (continued):
Sharing a sentence is not in itself a finding about the gene and the disease.
rosacea (continued). "We further detected the expression of TLR7 in the skin biopsies from rosacea patients and HS through immunohistochemistry (IHC), and found TLR7 was abundantly located in cytoplasm mainly in epidermal keratinocytes of lesional skin from rosacea patients." (PMID 37780385, 2023). "Among these TLRs, TLR7 is overexpressed in both rosacea patients and mouse models." (PMID 37780385, 2023). "In consideration of the chemotactic effect of chemokines on immune cells, as well as the enrichment of immune cells in rosacea lesions, we performed CD4 immunostaining and found infiltration of CD4+ T cells induced by LL37 was eliminated by Tlr7 siRNA in the dermis of rosacea-like mice." (PMID 37780385, 2023). "Silencing TLR7 prevented the development of rosacea in LL37-induced rosacea-like mouse models." (PMID 37780385, 2023). "Therefore, we wonder if TLR7 or TLR8 expressed by specific skin cells are involved in the pathogenesis of rosacea." (PMID 37780385, 2023). "In addition, the fold change of TLR8 and TLR7 ranked as the top two among these TLRs, suggesting that they may take part in the procession of rosacea." (PMID 37780385, 2023). "However, our research provided evidence that TLR7 is dramatically overexpressed in keratinocytes in rosacea patients, which could also be induced by LL37 in mice." (PMID 37780385, 2023). "Rosacea patients also showed elevated LL-37 expression and enhanced CD4+ T-cell infiltration, highlighting TLR7 and LL-37 as crucial molecular triggers in disease pathogenesis." (PMID 41373451, 2025). "Ultimately, TLR7/NFκ B/mTORC1 axis promotes the production of cytokines and chemokines, leading to the migration of CD4+T cells, which are infiltrated in the lesional skin of rosacea." (PMID 37780385, 2023). "In order to figure out whether TLR8 and TLR7 act in the etiology of rosacea, we detected the expression of TLR8 or TLR7 in skin samples of participants and conducted a correlation analysis between its mRNA levels and disease severity (including CEA scores and IGA scores) among 24 patients." (PMID 37780385, 2023). "Besides TLR2, our RNA‐sequencing data also showed that other TLRs (e.g., TLR4, TLR7, and TLR8) were also significantly increased in rosacea, but the role of these TLRs remains unclear in the pathogenesis of rosacea." (PMID 33734592, 2021). "To further verify that TLR7 regulates NFκB signaling in rosacea, we performed immunofluorescence staining on mouse skin lesions and found cathelicidin LL37 increased the expression of p-p65 in epidermis, which was not apparent in Tlr7 siRNA mice." (PMID 37780385, 2023).
SARS-CoV infection (4 papers, 2009 to 2023). "Because of the high homology between SARS-CoV-2 and SARS-CoV, it was currently thought that changes in TLR7 expression after SARS-CoV infection of cells or animals could be used as a reference for SARS-CoV-2." (PMID 37362864, 2023). "The results showed that TLR7 expression levels increased following SARS-CoV infection." (PMID 37362864, 2023). "Both groups suggested the involvement of TLR7/MyD88/IFNα dependent signaling and further exploration is needed to determine if TLR7 agonist may elicit potent antiviral effects against SARS-CoV infection." (PMID 19505311, 2009). "The authors demonstrated that SARS-CoV also induced a strong Type I interferon response in human pDCs and proposed that TLR7 may play a similar role in SARS-CoV infection." (PMID 19505311, 2009). "IFNAR2, TLR7 and JAK1 genes connect SARS-CoV infections and potential therapeutics for SARS." (PMID 36553678, 2022).
squamous cell carcinoma (4 papers, 2017 to 2024). A carcinoma arising from squamous epithelial cells. "Summarizing the Results section, significant differences were observed in the expression of various TLRs (TLR-2, TLR-3, TLR-4, TLR-7, TLR-8, and TLR-9) on selected T and B cell subpopulations between the patients with squamous cell carcinoma (SCC) and the healthy controls." (PMID 39124797, 2024).
T cell lymphoma (4 papers, 2015 to 2023). "In our hands, the systematic application of the TLR7/8 ligand R848 was also inefficient in increasing the survival of SJ3 T cell lymphoma-bearing mice." (PMID 34330751, 2021). "The expression levels of TLR1, TLR4, TLR7, and TLR9 increased in the LNs of patients with AOSD compared to that in reactive LN or T cell lymphoma." (PMID 35715478, 2022). "The expression levels of TLR1, TLR4, TLR7, and TLR9 were higher in LNs of patients with AOSD than in those with T cell lymphoma and reactive lymphadenopathy." (PMID 35715478, 2022). "The table summarizes the mean percentages of inflammatory cells expressing TLR1, TLR2, TLR4, TLR7, and TLR9 in LNs from patients with AOSD, tuberculosis (Tb) lymphadenitis, T cell lymphoma, histiocytic necrotizing lymphadenitis (HNL), and reactive LNs." (PMID 35715478, 2022). "The expression level of TLR2 was similar in LNs from patients with T cell lymphoma and AOSD; however, TLR1, TLR4, TLR7, and TLR9 expression levels were higher in the LNs of patients with AOSD than in T cell lymphoma." (PMID 35715478, 2022). "The expression levels of TLR1, TLR4, TLR7, and TLR9 were higher in LNs of patients with AOSD than in LNs of those with T cell lymphoma and reactive lymphadenopathy." (PMID 35715478, 2022). "We have synthesised a novel TLR7 agonist called SZU-101 and investigated the systemic antitumour effect on a murine model of T cell lymphoma in vivo." (PMID 25887995, 2015). "Furthermore, the percentage of inflammatory cells expressing TLR4, TLR7, and TLR9 in LNs from patients with AOSD was significantly greater than that in patients with T cell lymphoma (p = 0.001) and reactive LNs (p = 0.012)." (PMID 35715478, 2022). "In our murine model of T cell lymphoma, the application of a conventional chemotherapeutic agent, DOX, which is a component of CHOP therapy, in combination with TLR7 agonist SZU-101, significantly improved survival compared with PBS treatment or DOX treatment alone." (PMID 25887995, 2015).
tuberculosis (4 papers, 2013 to 2022). A chronic, recurrent infection caused by the bacterium Mycobacterium tuberculosis. "Apart from targeting the major metabolic pathways, there are various drugs reported to limit Leishmania infection by different mechanisms, such as using the adenosine analogues, anti-tuberculosis drug delamanid, dihydropyrimidine-based derivatives, TLR7 agonist, and curdlan." (PMID 36015216, 2022). "In support of this hypothesis, the TLRs are upregulated as a group in both melioidosis (TLR1, TLR2, TLR4, TLR5, TLR6, TLR8 and TLR10) and tuberculosis (TLR2, TLR4, TLR5, TLR6, TLR7, TLR8)." (PMID 23383015, 2013).
Turner syndrome (4 papers, 2018 to 2024). Turner syndrome is a chromosomal disorder associated with the complete or partial absence of an X chromosome. "A similar study also investigated the effect of X chromosome number and sex hormones on the TLR7-mediated IFNα production by primary human pDCs from healthy females, males, transgender volunteers on hormone therapy, and females with Turner syndrome." (PMID 33919546, 2021). "Notably, according to a study including adults, prepubertal children, transgender men and women, and individuals with Turner syndrome, the IFN-1 production from TLR7-activated DCs is associated with the number of X chromosomes." (PMID 38835761, 2024). "In order to assess whether X chromosome number or serum sex hormone concentration accounted for the increase in TLR7 expression in post-pubertal females, the model was again extended to include transgender volunteers and those with Turner's syndrome." (PMID 30705679, 2018).
uveitis (4 papers, 2019 to 2025). An inflammatory process affecting a part of or the entire uvea. "Pathogenic T cells might shape RPE cells and induce higher TLR7 expression through direct or indirect pathways by the stimulation of DAMPs that might have been produced by T cell-mediated tissue damage in uveitis." (PMID 35069523, 2021). "For instance, in the uveitis only group, the genes KLHL21, MYLIP, ZNFX1, PDE4A, TNFRSF21, and N4BP2L2 were downregulated, while METTL72, GAPT, CD180, CCR2, and TLR7 were upregulated when comparing uveitis patients with healthy controls." (PMID 40270958, 2025). "In summary, our results elucidate the role of TLR7 signaling in EAU pathogenesis by affecting the characteristics of RPE and pathogenic T cells in uveitis." (PMID 35069523, 2021). "Cluster 3 (C3) represented a gene signature associated with uveitis that includes core B cell genes, including the MS4A1 gene (encoding CD20), Toll-Like Receptors (TLR) TLR7 and CD180 that regulates B cells responses, and ITSN2 a key gene required for antibody formation in B cells." (PMID 33042130, 2020). "Moreover, TLR7 signaling also affects the barrier function of RPE cells, and such impaired BRB function in uveitis results in a positive feedback loop with increased pathogenic T cell infiltration in the ocular environment, leading to the exacerbation of uveitis severity." (PMID 35069523, 2021). "For instance, metaDEGs of the uveitis only group comprise genes that are involved in the innate immune response, such as chemokine receptors (CX3CR1, CCR1, and CCR2), and Toll-like receptors (TLR4, TLR7, TLR8, and the TLR4 homologous receptor, CD180)." (PMID 40270958, 2025). "Several metaDEGs from the uveitis only group, including IFIT3, IFI44, IFITM1, MX1, TLR7 and DHRS9, and gene hubs from the modular co-expression analyses of the systemic disease-associated uveitis group are critical players in interferon-induced immune responses." (PMID 40270958, 2025).
viral hepatitis (4 papers, 2014 to 2020). An acute or chronic inflammation of the liver parenchyma caused by viruses. "In this review, we will focus primarily on TLR7, as the majority of small molecule TLR agonists undergoing clinical development for treatment of viral hepatitis target TLR7 agonists to induce an endogenous interferon response." (PMID 24884741, 2014).
acute lymphoblastic leukemia (3 papers, 2014 to 2026). Leukemia with an acute onset, characterized by the presence of lymphoblasts in the bone marrow and the peripheral blood. "In acute lymphoblastic leukemia (ALL) cell lines, TLR1, TLR2, TLR3, TLR4, TLR6 and TLR7 are expressed albeit at variable levels." (PMID 25112836, 2014). "As the most common pediatric malignancy, the B-cell precursor acute lymphoblastic leukemia (BCPALL) expresses detectable alterations in costimulatory molecule expression of TLR2, TLR7, and TLR9, being TLR2 ligands PAM3CSK4 and PGN, the most powerful effect on anti-ALL immune responses." (PMID 37822929, 2023).
avian influenza (3 papers, 2012 to 2021). Infection of domestic and wild fowl and other birds with influenza A virus. "TLR7 is thought to play a role in immunity to viruses (e.g. avian influenza in Pekin duck Anas platyrhynchos domesticus) and loss or gain of TLR loci among derived lineages may reflect differences in selection pressures during the evolutionary histories of those taxa." (PMID 23024782, 2012). "Molecular docking revealed RIGI, TLR3, and TLR7 as the promising genes conferring antiviral immunity against avian influenza." (PMID 34970593, 2021). "The binding of TLR7 of duck with the neuraminidase H5N1 strain of avian influenza is being depicted with certain domains highlighted." (PMID 34970593, 2021). "The binding of TLR7 of duck with the hemagglutinin H5N1 strain of avian influenza is being depicted with certain domains highlighted." (PMID 34970593, 2021). "The future outcome for the current study is the possible utilization of the identified disease resistant genes (RIGI, TLR3, and TLR7) for the development of avian influenza–resistant chicken with the identified gene insert from duck through gene editing or a transgenic approach." (PMID 34970593, 2021). "Binding for H and N antigens was observed for different strains of avian influenza with RIGI, TLR7, and TLR3." (PMID 34970593, 2021).
bacterial sepsis (3 papers, 2013 to 2025). "Notably, we demonstrate the contribution of TLR7, a single-stranded RNA sensor, to the development of procoagulant, but also to hypofunctional platelets, in a bacterial sepsis model." (PMID 41301522, 2025). "Taking into account that bacterial RNA triggers TLR7 and TLR8 pathways, one may speculate that TLR7/8 agonists would impact on bacterial sepsis." (PMID 24302927, 2013).
Cachexia (3 papers, 2015 to 2025). Severe weight loss, wasting of muscle, loss of appetite, and general debility related to a chronic disease. "Consistent with prior studies, KxPxCx allograft-induced cachexia resulted in hypothalamic inflammation in vehicle-treated animals, with increases in expression of Selp, Il1b, Il1r1, Tlr7, Ccl2, and Icam1." (PMID 31615993, 2019). "Based on the lack of tumor reduction and exacerbation of cachexia in TLR7-deficient hosts, we report that the beneficial effects of R848 require host rather than neoplastic TLR7." (PMID 31615993, 2019). "Indeed, although there was no decrease in food intake or body weight associated with treatment induction, due to these adverse effects being on-target and mediated exclusively through TLR7 in mouse, treatment groups began to diverge significantly during the cachexia stage." (PMID 31615993, 2019). "For instance, tumor-derived sEVs enriched in miR-21 have been shown to activate Toll-like receptors 7 and 8 (TLR7/8), inducing proinflammatory cytokines such as IL-6 and TNF-α, and promoting cachexia in murine cancer models." (PMID 40806377, 2025). "More importantly, neither TLR7/9 blockade nor genetic deletion of TLR9 improved overall mortality or the metabolic changes of pancreatic cachexia in our validated mouse model." (PMID 26172047, 2015).
common variable immunodeficiency (3 papers, 2013 to 2023). "Perhaps the most convincing evidence for the involvement of TLR7/9 signaling in B cells for anti-DNA antibody production comes from the case studies of SLE patients that develop an antibody deficiency syndrome similar to common variable immunodeficiency (CVID)." (PMID 31354738, 2019). "An interesting report describes remission of SLE in a patient which was attributed to unresponsiveness to both TLR-7 and -9 stimulation after development of common variable immunodeficiency – (CVID-) like disease." (PMID 24109483, 2013). "In this study, we aim to unravel the intricate involvement of TLR2, TLR4, TLR3, TLR7, TLR8, and TLR9 in the immunopathogenesis of common variable immunodeficiency—CVID (as PID)—and chronic lymphocytic leukemia—CLL (as SID)." (PMID 37626865, 2023).
cutaneous lupus erythematosus (3 papers, 2025). An autoimmune disorder that manifests as different lupus-specific skin disorders; it can occur with systemic lupus erythematosus, or as a singular disease. "Importantly, the molecular docking study further confirmed that afimetoran binds strongly to both mutant and wild type TOLLIP protein, and afimetoran has been recently reported in clinical study of Cutaneous Lupus Erythematosus, as toll like receptor 7/8 (TLR7/8) antagonist." (PMID 41231851, 2025). "Furthermore, HCQ levels in the blood of patients with cutaneous lupus erythematosus correlated negatively with the IFNα-producing capacity of their pDCs upon TLR9 stimulation, with a weaker correlation observed upon TLR7/8 stimulation." (PMID 40746538, 2025). "Also, another study on discoid lupus and cutaneous lupus erythematosus (CLE) identified that pDCs are not major producers of type I interferons, as they exhibit markedly reduced IFN-α production upon toll like receptor 7 (TLR7) stimulation." (PMID 40791585, 2025).
dacryoadenitis (3 papers, 2020 to 2024). Inflammation and enlargement of the lacrimal gland. "Neither WT nor Tlr7 KO female mice developed lacrimal gland inflammation in accordance with the known male-specific occurrence of spontaneous lacrimal gland autoimmunity in NOD mice." (PMID 33322152, 2020).
dermatomyositis (3 papers, 2020 to 2023). Dermatomyositis (DM) is a type of idiopathic inflammatory myopathy characterized by evocative skin lesions and symmetrical proximal muscle weakness. "Enriched genes including S100A12, MPO (myeloperoxidase), S100A8, CXCL10, S100A9, CD244, CD244,and TLR7 have been linked to dermatomyositis." (PMID 38137330, 2023). "The mechanism of vaccine-induced dermatomyositis remains unknown although we speculate that it may be promoted by aberrant TLR7 signaling, and possible molecular mimicry between viral spike glycoproteins, anti-idiotype antibodies, and dermatomyositis autoantigens." (PMID 36419787, 2022).
epilepsy (3 papers, 2019 to 2025). A brain disorder characterized by episodes of abnormally increased neuronal discharge resulting in transient episodes of sensory or motor neurological dysfunction, or psychic dysfunction. "It is pointed out that TLR7 is widely expressed in tuberous sclerosis lesions, which is an essential cause of drug‐resistant epilepsy." (PMID 40103702, 2025). "Fei Xiao, Xuefeng Wang, and colleagues at Chongqing Medical University in China detected activation of TLR7 in mouse neurons during the cellular changes that underly a susceptibility to epilepsy." (PMID 37258573, 2023). "Studies using a mouse model of epilepsy implicate a protein inside cells called Toll-like receptor 7 (TLR7) in susceptibility to epileptic seizures, suggesting the protein could be a target for antiepileptic drugs." (PMID 37258573, 2023). "However, the specific mechanism of TLR7 causing epilepsy is still unclear." (PMID 40103702, 2025). "Our results indicated that TLR7 is an important factor in regulating epileptogenesis, suggesting a possible therapeutic target for epilepsy." (PMID 37258573, 2023). "TLR7 is activated in neurons in the early stage of epilepsy." (PMID 40103702, 2025). "The present study determined TLR7 mRNA expression during different stages of epilepsy." (PMID 37258573, 2023). "Subsequent work may lead to opportunities for the use of neuroimaging and TLR7 inhibitors in a personalized approach to treating intractable epilepsy." (PMID 31511910, 2019). "TLR7 activation by microRNAs may contribute to the neuroinflammatory cascade in epilepsy in TSC." (PMID 31511910, 2019).
fungal infection (3 papers, 2020 to 2023). "In recent years, the role of intracellular pattern recognition receptors (TLR3, TLR7, TLR8, and TLR9) has become increasingly important in the pathophysiology of some mycoses, such as paracoccidioidomycosis, cryptococcosis, aspergillosis, and candidiasis." (PMID 37233274, 2023). "In recent years, the role of intracellular pattern recognition receptors (TLR3, TLR7, TLR8, and TLR9) has become increasingly important in the pathophysiology of some mycoses, as paracoccidioidomycosis, cryptococcosis, aspergillosis, and candidiasis." (PMID 33194839, 2020). "In this section, we will discuss the role of TLR3, TLR7, and TLR9 in the main fungal infections, such as candidiasis, aspergillosis, paracoccidioidomycosis, cryptococcosis, and histoplasmosis." (PMID 33194839, 2020).
Graves disease (3 papers, 2014 to 2017). Graves' disease is an autoimmune disorder that leads to overactivity of the thyroid gland (hyperthyroidism).It is caused by an abnormal immune system response that causes the thyroid gland to produce too much thyroid hormones. "On a genetic level, TLR7 SNPs have been associated with Graves' disease and SLE." (PMID 26442097, 2015).
H1N1 influenza (3 papers, 2019 to 2026). "In H1N1 influenza, viral RNA is recognized by host intracellular receptors (e.g., RIG-I or TLR7), which activate the IKK complex and release NF-κB." (PMID 41592028, 2026). "In a BALB/c mouse model, H1N1 influenza vaccine adjuvanted with a synthetic TLR7 agonist (imiquimod) showed higher efficacy against an early challenge with H1N1 compared to H1N1 influenza vaccine without an agonist, indicating the enhanced efficacy of the TLR7 agonist-adjuvanted vaccine." (PMID 38892096, 2024).